CD4 (CD4 molecule)
Diseases named in the same sentence as CD4 in open-access papers (continued):
Sharing a sentence is not in itself a finding about the gene and the disease.
influenza (continued). "Mucosal tonsillar and peripheral blood CD4 T-cell proliferation was evaluated in response to pneumococcal, influenza and MTB-PPD antigens in children (age 1–12 years) and older children and adults (≥13–41)." (PMID 23284694, 2012). "We have also shown that asymptomatic HIV-infected African adults have considerable signs of immune dysregulation with impaired influenza-specific CD4+ T-cell responses in the lung." (PMID 22715399, 2012). "In industrialised countries, the introduction of highly-active antiretroviral therapy (HAART) has led to some reduction in influenza-associated complications among HIV-infected persons, which appears to be related to the increase in CD4 count." (PMID 22715399, 2012). "We show that vaccination with influenza-LACK158–173 triggers LACK158–173-specific Th1-biased CD4+ T cell responses within an appropriate cytokine milieu (IFN-γ, IL-12), essential for the magnitude and quality of the Th1 response." (PMID 22470440, 2012). "In humans, protection against influenza H3N2 or H1N1 challenge correlated with pre-existing influenza-specific CD4+ T cells." (PMID 23240067, 2012). "CD4+ T-cells are important in anti-influenza defence, they provide help to B-cells which leads to production of antibodies necessary to complete viral clearance." (PMID 22715399, 2012). "We have demonstrated widespread influenza-specific CD4+ T-cell immunity in a healthy African adult population, which is impaired in HIV-infected individuals even after immune reconstitution with HAART for 12months." (PMID 22715399, 2012). "The CD4 T cell response to influenza infection has long been regarded as “Th1-polarized” and characterized by high levels of IL-2 and interferon (IFN)-γ secretion." (PMID 22457834, 2012). "This poor immune reconstitution was characterised by a low influenza-specific proliferative CD4+ T-cell response and reduced proportions of CD154-expressing influenza-specific CD4+ T-cells in peripheral blood." (PMID 22715399, 2012). "The M2e peptide contains an MHC class II-restricted epitope, and studies have documented that influenza-specific CD4+ T cells are involved in immune protection." (PMID 23285063, 2012). "The current study was initiated to relate patterns of cytokine secretion by influenza-specific CD4 T cells to epitope specificity and the magnitude of epitope-specific responses." (PMID 22457834, 2012). "Optimal virus-specific Ab production by B cells following influenza infection is dependent on CD4 T cell help." (PMID 22457834, 2012). "CFSE proliferation and CD154 expression flow cytometry-based assays were used to measure influenza-specific CD4+ T-cell immunity." (PMID 22715399, 2012). "Our findings indicate that host factors modulate influenza-specific CD4 T cell and B cell responses in a lung-restricted fashion." (PMID 22457834, 2012). "In conclusion, healthy African adults have a robust influenza-specific CD4+ T-cell immunity similar with other populations with a known high prevalence rate of influenza infection." (PMID 22715399, 2012). "In order to assess protective efficacy of LACK158–173-specific CD4+ T cells generated after a single i.p. immunisation with influenza-LACK158–173 viruses against Leishmania challenge, we performed immunisation trials in Balb/c mice." (PMID 22470440, 2012). "This prompted us to examine a conventional mouse strain with a defined NC-specific CD4 T cell repertoire and to conduct a parallel analysis of the influenza-specific B cell response." (PMID 22457834, 2012). "We also showed that IL-7 signaling was necessary for the generation of a robust influenza A-specific CD4 and CD8 T cell response and that this requirement is intrinsic to CD8 T cells." (PMID 23189186, 2012). "We have previously demonstrated strong naturally-acquired mucosal and systemic CD4+ T-cell immune memory to influenza antigens in healthy UK adults." (PMID 22715399, 2012).
influenza (continued). "To test this, we highly purified endogenous airway CD4+ T cells from a cohort of mice that were either challenged with a secondary influenza infection or left unchallenged." (PMID 21647373, 2011). "For example, in the early stage of influenza infection, CD4+ cells differentiate into T-helper 1 cells (Th1) and a bias towards Th1 cells development protects host from severe infection." (PMID 21408152, 2011). "Parenteral influenza vaccination results in significant increase in the antigen-specific CD4+ Th cell population after vaccination." (PMID 22393340, 2011). "Similar phenomenon of CD8+ T cell selective tolerance induction in the presence of normal CD4+ T cell and antibody responses was observed in transgenic mice that express influenza HA protein in the lung and to a lesser extent in the thymus." (PMID 21858191, 2011). "The essential role of B-cells together with CD4+ cells in enabling a T-dependent antibody response and recovery from influenza infection has been shown." (PMID 22039539, 2011). "Here, we used a model of heterosubtypic influenza infection to study the reactivation of CD4+ T cells present in the lung airways at the time of secondary challenge." (PMID 21647373, 2011). "Virosomes are potent stimulators of mucosal immunity and SL vaccination with the c-di-GMP adjuvanted H5N1 virosomes induced both local and systemic antibody responses and high frequencies of influenza-specific homo- and hetero-subtypic CD4+ Th1 cells." (PMID 22069479, 2011). "Here we use a mouse model of secondary heterosubtypic influenza infection to show that CD4+ T cells in the lung airways are reactivated within 24 hours of secondary challenge." (PMID 21647373, 2011). "In particular, we recently described a unique population of tissue-memory CD4+ T cells recovered from the lungs of influenza immune mice." (PMID 21647373, 2011). "Influenza infection induces a strong CD4+ T-helper (Th) response, which plays an important role in stimulating antibody production against the virus." (PMID 22393340, 2011). "Protective immunity in the lungs of influenza infected mice is also characterized by CD4 and CD8 T cells with a multi-functional phenotype." (PMID 21720558, 2011). "Based on pre-clinical studies, it is generally assumed that during vaccine inoculation, influenza antigen-specific CD4 T-cells provide essential T-cell help for B-cells recognizing synthetic non-influenza peptides coupled to the surface of virosomes." (PMID 21799810, 2011). "Parenteral influenza vaccination results in significant increase in the CD4+ Th cell population after vaccination." (PMID 22393340, 2011). "A recent report by the Swain lab has furthered our understanding of the early tissue response by demonstrating CD4-dependent alterations in the lung innate inflammatory cytokine milieu in the first two days of secondary influenza infection." (PMID 21647373, 2011). "All permutations of the produced cytokines were summed to measure the total frequency of influenza specific CD4+ Th1 cells." (PMID 22069479, 2011). "In contrast, depletion of the spleens from influenza specific CD4 T-cells was observed at that time point, within three days after infection CD4 frequencies have dropped by 60%." (PMID 20808939, 2010). "High frequencies of influenza-specific CD4 and CD8 cells were induced by vaccination with the MVA-based HA vaccine, not only in the spleens but also in the lungs, although the frequencies were slightly lower in the lungs." (PMID 20808939, 2010). "Multiparametric flow cytometry assays were performed to determine the relative importance of the subpopulations of influenza-specific CD3+CD4+ and CD3+CD8+ T cells that produce IL-2, IFN-γ, and TNF-α." (PMID 20520820, 2010). "While a CCR2 deficiency led to attenuated percentages of tipDCs in influenza-infected mice compared to controls, as previously reported, percentages of CD69+, CD4 and CD8 T cells were significantly attenuated in CCR2 deficient mice." (PMID 20967263, 2010).
influenza (continued). "Blood feeding by D. andersoni pathogen-free nymphs or intradermal injection of salivary gland extracts programs influenza hemagglutinin influenza peptide specific TCR transgenic CD4+ T cells to express IL-4." (PMID 19814808, 2009). "It is possible that IL-15 present in the lungs of influenza infected mice (as detected from our whole lung mRNA array data) shuts down part of the APC function of IKDCs for CD4 T cells, as recently demonstrated in vitro." (PMID 19784375, 2009). "CDCs induced strong CD4 T cell proliferation ex vivo following influenza infection (48% recruited into cell division), whereas IKDCs only induced the proliferation in 3% and B220−NK cells in 5% of co-cultured CD4 T cells." (PMID 19784375, 2009). "We co-cultured these DC subsets with CSFE-labeled influenza HA-specific naïve TCR tg CD8+ or CD4+ T cells to evaluate the capacity of these LN-derived DC subsets to drive naïve T cell activation/differentiation." (PMID 19145246, 2009). "It was therefore striking to see that IKDCs hardly presented influenza derived antigen to specific CD4 T cells, whereas cDCs readily did under these conditions." (PMID 19784375, 2009). "This protection required B cells indicating that the classical helper function of CD4 T-cells is important in protection against influenza, although functional diverse subsets of CD4 Th have been described including some with cytotoxic activity." (PMID 21994580, 2009). "The H5N1-specific CD4 responses seen in some 6–35 month-old children is likely to be due to cross reactive T-cell responses stimulated by prior infection by other influenza strains." (PMID 19112513, 2008). "When the extent of CD4 T-cell–mediated immunity before and after seasonal influenza vaccination was compared in the healthy donors enrolled in the study, a nonhomogeneous pattern of responses was detected." (PMID 18258091, 2008). "In light of the ability of IL-6−/− mice to generate a comparable CD8+ T cell response to WT mice, influenza-specific CD4+ T cell responses were also assessed in both groups of mice." (PMID 18389078, 2008). "Although both WT and IL-6−/− mice elicited primary responses to influenza infection, the overall profile of CD4+ T cell infiltrating of the lung indicates that the T cell response was slightly delayed in IL-6−/− mice consistent with previous reports." (PMID 18389078, 2008). "Baseline percentage of influenza-specific IFN-γ+ CD4 T-cells was identified as a significant correlate of CD4 and CD8 T-cell responses, with lower baseline levels associated with larger T-cell responses." (PMID 18596908, 2008). "We demonstrate that influenza-induced IL-6 limits the activity of virus-specific Tregs, thereby facilitating the activity of virus-specific memory CD4+ T cells." (PMID 18389078, 2008). "These were adult age group (weakest candidate) and baseline percentage of flu-specific CD4 T-cells (strongest candidate)." (PMID 18596908, 2008). "We focused on three of our measured parameters that are believed to represent critical characteristics of protective immunity: HAI titer and the frequency of influenza-specific CD4 and CD8 T-cells in the peripheral blood." (PMID 18596908, 2008). "The impact of IL-6 on the influenza-specific T cell response appears to be selective for CD4+ T-cells implying that IL-6 has a different effect on the behavior of CD4+ and CD8+ T cells." (PMID 18389078, 2008). "In this study we compared influenza-specific CD4+ and CD8+ T cell memory after infection of wild-type (WT) and IL-6 deficient (IL-6−/−) C57BL/6 (B6) mice with influenza virus." (PMID 18389078, 2008). "In this respect, depletion of CD25+ cells had a variable affect on proliferative responses observed in WT mice, removal of CD25+ cells uncovered influenza-specific memory CD4+ T cell responses in the majority of IL-6−/− mice." (PMID 18389078, 2008). "The experiment was performed in Cd59a–/– mice due to the higher number of CD4/CD8 DP cells recruited in lungs after influenza infection." (PMID 17429844, 2007).
influenza (continued). "Influenza-specific proliferation of CD4+ T cells was significantly increased in Cd59a–/– compared to WT mice at all time points tested." (PMID 17429844, 2007). "An increased frequency of single-positive CD4+ T cells was observed in the lungs of influenza-infected Cd59a–/– compared to WT B6 mice." (PMID 17429844, 2007). "Phenotypic analyses of the cells infiltrating the lungs of influenza-infected mice revealed a large population of CD4/CD8 DP lymphocytes." (PMID 17429844, 2007). "In contrast, numbers of infiltrating CD4+ T cells remained unchanged after sCR1 administration, indicating that modulation of the CD4+ T cell response by CD59a in experimental influenza infection is complement-independent." (PMID 17429844, 2007). "Analysis of cells infiltrating the lungs of influenza-infected WT and Cd59a–/– mice revealed a population of CD4/CD8 DP cells appearing early in the course of infection." (PMID 17429844, 2007). "Several investigators have introduced external epitopes in influenza to follow CD4+ T-cell responses in defined systems." (PMID 16494717, 2006). "Still, a substantial amount of work has been done with various knockout, depletion, and cell-transfer models to investigate the role of CD4+ T cells in primary, secondary, and memory responses to influenza infection in the mouse model." (PMID 16494717, 2006). "In the influenza model, although the draining lymph node and spleen CD8+ responses were defective in secondary infection of CD4+ T cell–deficient mice, the CD8+ T-cell responses in bronchoalveolar lavage were equivalent to those seen in wild-type mice." (PMID 16494717, 2006). "In contrast to the body of literature that has characterized the role of CD8+ T cells specifically in models of influenza infection, relatively little is known about the role of CD4+ T cells as direct mediators of effector function." (PMID 16494717, 2006). "This lower response is related with CD4 count less than 500 cel/mm3, and has also been found with other antigens like influenza or pneumococcal vaccines." (PMID 16600028, 2006). "Previous studies with other antigens (like influenza or 23-valent pneumococcal vaccines) have shown lesser response asocciated with lower CD4 counts." (PMID 16600028, 2006). "We review the literature on the role of CD4+ and CD8+ T cell–mediated immunity in influenza infection and the available data on the role of these responses in protection from highly pathogenic influenza infection." (PMID 16494717, 2006). "HLA-DR*1101-Bir molecules can be pulsed with at least three different promiscuous peptide epitopes, derived from Tetanus Toxoid, influenza HA and the tumour associated antigen MAGE-3 respectively, to stain specific CD4+ T cells." (PMID 16329759, 2005). "This study demonstrates that D + Q treatment prior to NP vaccination did not improve vaccine‐induced NP IgG antibody titers, CD4 T cell responses in the spleen or overall flu outcomes including flu‐induced weight loss, lung viral load and lung pathology." (PMID 41462563, 2026). "CD8+ T cells directly eliminate influenza‐infected cells through cytotoxicity, while CD4+ T cells contribute to viral clearance, differentiate into Th1/Th2/Th17 subsets, support B‐cell antibody production, and activate CD8+ T cells to establish long‐term memory." (PMID 41409094, 2025). "The strength of influenza vaccine responses could be predicted by the frequency of circulating immune cell subsets including effector memory (EM) CD4+ T cells, activated CD4+ and CD8+ T cells, dendritic cells (DCs), as well as CD20+CD38+ B cells." (PMID 39938525, 2025). "Furthermore, multiple studies have reported increased IFN-γ following influenza vaccination, while IL-15 as an adjuvant boosts CD4 T-cell immunity." (PMID 40881708, 2025). "She had a CD4 T lymphocyte count of 644 mm3 and was hospitalized with a diagnosis of influenza." (PMID 40260188, 2025).
influenza (continued). "Existing influenza‐specific cellular responses that are H5Nx virus cross‐reactive are also present within populations of unexposed individuals, as evidenced by CD4+ (and CD8+) memory T‐cell reactivity predominantly recognising internal proteins of avian viruses." (PMID 41395356, 2025). "Importantly, post influenza infection B-IL1β-/- also have noticeably less infiltration of CD4 + T cell into the GC and even the follicular areas, compared to B-WT mice." (PMID 40825032, 2025). "Purified CD4+ T cells from medLNs of influenza-infected WT (Prdm1fl/fl) and Prdm1-CKO (Prdm1fl/flCD4cre) mice were treated with IL-2 for 24 hours after ex vivo influenza-specific peptide (NP311–325) stimulation and subjected to RNA sequencing (RNA-seq) analysis." (PMID 40680114, 2025). "Interestingly, a more recent influenza study in 53 older subjects found that miR-150 was correlated with immune outcomes across several cell types, particularly in CD4+ T cells." (PMID 40006728, 2025). "The influenza vaccine work in 53 older subjects found a more consolidated group of three, miR-150, 629, and 4443, that were correlated with immune outcomes across several cell types particularly in CD4+ T cells." (PMID 40006728, 2025). "TGF-β signaling polarize CD4+ T cells into Tregs during influenza infection." (PMID 40872830, 2025). "In addition to their helper activity, CD4+ Tem cells play a protective role during influenza infection, which has been described in animal models." (PMID 41295490, 2025). "These CD4+ TRM cells conferred significant protection against heterosubtypic influenza infections in both mice and ferrets, highlighting the potential of this approach to overcome the strain-specific limitations of current vaccines and provide broader respiratory tract protection." (PMID 40407543, 2025). "CD4+ strain–specific T-cell responses were detected at day 8 and were sustained or stronger at day 29 for all mRNA-1010 groups, with the greatest frequency observed for influenza B strains." (PMID 38934845, 2025). "Thus, BLIMP1 limits IL-2–STAT5 signaling in ex vivo–isolated splenic Treg cells as well as in influenza-infected mouse CD4+ T cells." (PMID 40680114, 2025). "CD4+ T cells were then stimulated with IL-2 and influenza-specific peptide (nucleoprotein NP311–325), and NP311–325 tetramer–positive CD4+ T cell populations including T follicular helper (TFH), T follicular regulatory (TFR), TEFF, and conventional Treg (cTreg) cells were analyzed." (PMID 40680114, 2025). "Indeed, blocking CXCR3-mediated trafficking during influenza infection in mice resulted in an accumulation of influenza-specific CD4+ T cells in the T-cell zone and an impaired B-cell response." (PMID 39932316, 2025). "This strongly suggests that CD4+ T cells may exert direct protective effects in response to influenza." (PMID 40568589, 2025). "Furthermore, and LNP-formulated influenza vaccine induced the stimulation and activation of antigen-specific CD4+ T follicular helper cells and germinal center B cells via IL-6 cytokine induction from lymph nodes." (PMID 40432140, 2025). "In addition, during the H1N1 epidemic, about half of influenza patients experienced a reduced CD4:CD8 ratio." (PMID 38601162, 2024). "It has been established that both live-attenuated and inactivated influenza vaccines can induce a robust antigen-specific CD4+ T cell response, whereas the induction of CD8+ T cell responses tends to be more pronounced after infection and challenging to elicit with inactivated influenza vaccines." (PMID 39340066, 2024). "Additionally, Dorea exerted a positive effect on influenza by modulating the amount of HLA DR+ CD4+ T cell %T cells, which mediated 15.31% of the total effect." (PMID 39062949, 2024). "Given that influenza-specific CD4 + T cells can exhibit direct antiviral activity, we hypothesize that CyCMV/Flu-elicited CD4 + T cells mediated protection by directly inhibiting viral replication." (PMID 39030218, 2024).